RNU6-194P (RNA, U6 small nuclear 194, pseudogene)
Gene: Small nuclear RNA gene on chromosome 6 (119,327,281 to 119,327,385, forward strand). Ensembl gene ENSG00000200732.
Homologues: Orthologues: chimpanzee U6 (97% identical), macaque U6 (86% identical), pig U6 (69% identical), pig U6 (62% identical), guinea pig U6 (52% identical), mouse Gm54604 (52% identical). Paralogues in human: RNU6-639P (83% identical), RNU6-1145P (82% identical), RNU6-16P (82% identical), RNU6-333P (82% identical), RNU6-38P (82% identical), RNU6-477P (82% identical), RNU6-1316P (81% identical), RNU6-393P (81% identical), RNU6-73P (81% identical), RNU6-921P (81% identical), RNU6-10P (80% identical), RNU6-1200P (80% identical), and 1285 more.